TNFSF12 (TNF superfamily member 12)
Diseases named in the same sentence as TNFSF12 in open-access papers (continued):
Sharing a sentence is not in itself a finding about the gene and the disease.
viral infections (3 papers, 2021 to 2025). "At the same time, certain monogenic causes of the CVID phenotype (e.g., NFKB1, NFKB2, TNFSF12/TWEAK/, TNFRSF13B/TACI/, or IKZF1/IKAROS/) have been reported to cause severe viral infections individually." (PMID 41229388, 2025).
Cirrhosis (2 papers, 2025). A chronic disorder of the liver in which liver tissue becomes scarred and is partially replaced by regenerative nodules and fibrotic tissue resulting in loss of liver function. "Additionally, the scar-associated macrophages (SAMs) differentiated by markers such as TREM2, CD9, SPP1, TNFSF12, and LGALS3 and PDGFRA+ myofibroblasts had an increased proportion in patients with cirrhosis." (PMID 39889710, 2025).
hemorrhagic stroke (2 papers, 2025). A stroke caused by a bleed on the brain. "Our study revealed that six druggable genes were associated with hemorrhagic stroke, and the inhibition of TNFSF12, SLC22A4, and SPARC had preventive effects against hemorrhagic strokes." (PMID 38977622, 2025). "Our study provides the first comprehensive exploration of targets involved in SAH and ICH using eQTL data to provide genetic support for hemorrhagic stroke drug development and is the first to report that TNFSF12, SLC22A4, and SPARC have preventive effects on IA, SAH, and ICH." (PMID 38977622, 2025). "We can conclude that TNFSF12, SLC22A4, and SPARC may induce IA, SAH, and ICH and that blocking these targets may have a protective effect against hemorrhagic stroke." (PMID 38977622, 2025).
influenza infection (2 papers, 2013 to 2025). "Detailed analysis of three proteins, USP47, TNFSF12 and TNFSF12/TNFSF12-13, confirmed that knocking down these proteins resulted in >85% protection from influenza-induced cell death." (PMID 23949218, 2013). "As our screens only identified loss of TNFSF13 or TNFSF12-TNFSF13 resulting in protection from influenza-induced cell death, this could suggest that TNFSF12 alone was not responsible for the cytotoxicity associated with influenza infection." (PMID 23949218, 2013).
leukemia (2 papers, 2025). A malignant (clonal) hematologic disorder, involving hematopoietic stem cells and characterized by the presence of primitive or atypical myeloid or lymphoid cells in the bone marrow and the blood. "In a patient with progressive disease, the expression of TNFSF12 in tumor cells indicates potential leukemia-instigated apoptosis of neighboring myeloid cells." (PMID 39975227, 2025). "Most notably, leukemia cells in patient 3 showed elevated expression of TNFSF12, which codes for a pro-inflammatory cytokine in the tumor necrosis factor (TNF) family called TWEAK, or TNF-like Weak Inducer of Apoptosis (also known as APO3L and CD255)." (PMID 40632867, 2025). "Most notably, leukemia cells in patient 3 showed elevated expression of TNFSF12, which codes for a proinflammatory cytokine in the tumor necrosis factor (TNF) family called TWEAK, or TNF-like Weak Inducer of Apoptosis (also known as APO3L, CD255)." (PMID 39975227, 2025).
aneurysm (1 paper, 2026). Bulging or ballooning in an area of an artery secondary to arterial wall weakening. "Golph3l upregulation by Klf5 facilitates TNF‐α and TNFSF12 secretion from AngII‐stimulated VSMCs by inducing Golgi compaction, which is essential for AIP and aneurysm development." (PMID 41317401, 2026).
dementia (1 paper, 2025). Loss of intellectual abilities interfering with an individual's social and occupational functions. "Our findings also covered well-known dementia-associated proteins, such as BCAN, CNTN5, and NCAN, along with identifying recently promising biomarkers, including IL18, MMP12, TNFSF12, and UNC5C, where these biomarkers presented the highest protein importance in their clusters." (PMID 40748327, 2025).
epilepsy (1 paper, 2024). A brain disorder characterized by episodes of abnormally increased neuronal discharge resulting in transient episodes of sensory or motor neurological dysfunction, or psychic dysfunction. "Tumor necrosis factor-β (TNF-β) levels (OR=0.9558, 95%CI =0.9151~ 0.9983, P=0.0417) and Tumor necrosis factor ligand superfamily member 12 (TNFSF12) levels (OR=0.9049, 95%CI =0.8443~ 0.9698, P=0.0047) were negatively associated with epilepsy." (PMID 39315097, 2024).
Hyperglycemia (1 paper, 2017). An increased concentration of glucose in the blood. "In the same line of evidence, we have not observed any differences in body weight, lipid profile or hyperglycemia between both Tnfsf12+/+ApoE−/− and Tnfsf12−/−ApoE−/− mice." (PMID 28447667, 2017).
intracerebral hemorrhage (1 paper, 2025). A cerebrovascular disorder characterized by bleeding into one or both cerebral hemispheres including the basal ganglia and the cerebral cortex. "The inhibition of TNFSF12, SLC22A4, and SPARC can reduce the risk of intracranial aneurysm, subarachnoid hemorrhage, and intracerebral hemorrhage." (PMID 38977622, 2025).
lung disease (1 paper, 2022). "Some of the pathways including the TWEAK pathway (TNFSF12-TNFRSF12A), ANXA1-FPR1, and LAMC2-CD44 have been reported previously in lung disease, which play a pivotal role in inflammatory immune mechanisms and immunosurveillance." (PMID 36605426, 2022).
lymphoma (1 paper, 2024). A malignant (clonal) proliferation of B- lymphocytes or T- lymphocytes which involves the lymph nodes, bone marrow and/or extranodal sites. "To address this question, we validated eight plasma proteins (IL-17A, F5, FLT4, SFTPB, and GNPTG in lymphoma, TNFSF12, CCL3, and KIT in NSCLC) for response prediction and three plasma proteins (IL36G, SERPINC1, and LTA) for relapse monitoring." (PMID 38349411, 2024).
periodontal diseases (1 paper, 2025). "Elevated levels of TWEAK/TNFSF12 have been suggested to be related to the exacerbation of periodontal diseases and contribute to RA pathogenesis by inducing the production of proinflammatory cytokines." (PMID 40151315, 2025).
thyroid cancer (1 paper, 2026). "MR analysis confirmed MERTK and MSR1 as genetic risk factors for thyroid cancer progression, whereas TNFSF12 exhibited protective effects." (PMID 41930700, 2026). "Functional experiments demonstrated that TNFSF12 enhances proliferative, invasive, and migratory capacities in thyroid cancer cells." (PMID 41930700, 2026).
viral encephalitis (1 paper, 2025). Encephalitis resulting from viral infection. "Beyond viral encephalitis, we found induction of the pathway in EAE, whereas for other brain diseases only limited parallel upregulation of microglial Tnfsf12 and oligodendrocyte Tnfrsf12a was observed." (PMID 40450318, 2025).
vitiligo (1 paper, 2024). Generalized well circumscribed patches of leukoderma that are generally distributed over symmetric body locations and is due to autoimmune destruction of melanocytes. "Interestingly, through MR analysis, we identified TNFRSF11B, TNF alpha induced protein 3 (TNFAIP3), TNF superfamily member 12 (TNFSF12) as potentially protective factors against vitiligo, which may explain why some patients experience depigmentation after using TNF inhibitors." (PMID 38660673, 2024).
xanthoma (1 paper, 2014). A non-neoplastic disorder characterized by a localized collection of histiocytes containing lipid. "We provide evidence that TNFSF12 deletion or TWEAK blockade promotes multiple features of atherosclerotic plaque stability in brachiocephalic arteries, including a reduction in the presence of lateral xanthomas, buried caps, medial erosion, calcium content and intraplaque haemorrhage." (PMID 24479820, 2014). "Both TNFSF12−/−ApoE−/− and anti-TWEAK-treated mice exhibited a reduced frequency of lateral xanthomas, medial erosion and presence of buried caps compared with TNFSF12+/+ApoE−/−." (PMID 24479820, 2014). "Moreover, TNFSF12 deletion or anti-TWEAK treatment reduces the presence of lateral xanthomas, aggregates of macrophage derived foam cells, which form fatty streaks along the margins of the established plaques 22, as well as buried caps, which may be the signature of silent plaque rupture." (PMID 24479820, 2014).
tumor (107 papers, 2006 to 2026). "Moreover, the expression of TNFSF12 was higher in the low AUCell score group, associated with tumor proliferation, invasion, migration, and angiogenesis." (PMID 37006250, 2023). "BIIB023 and RG7212 are both anti-TNFSF12 antibodies to potentially regulate inflammatory processes in neurons and tumor tissues, with ongoing clinical investigations (ClinicalTrials.gov identifier NCT01407406 for BIIB023 and NCT01383733 for RG7212)." (PMID 38443977, 2024). "The analysis discovered four subtypes of CAFs: one p-EMT tumor cell population, and cycling tumor cells as well as TNFSF12-TNFRSF25/TNFRSF12A interactions between CAFs and p-EMT tumor cells during tumor metastasis." (PMID 35742914, 2022). "The analysis discovered four subtypes of CAFs, one p-EMT tumor cell and cycling tumor cell population, as well as the roles of TNFSF12–TNFRSF25/TNFRSF12A interactions in CAFs and p-EMT tumor cells during tumor metastasis at the single-cell level." (PMID 35742914, 2022). "TNF Superfamily Member 12 (TNFSF12) belongs to the Tumor Necrosis Factor (TNF) protein family expressed in a range of organs, immune cell types, and tumor cells, which activates caspase 8 and caspase 9 and cause extrinsic and intrinsic apoptosis cascades." (PMID 35264191, 2022). "In order to study the specific effect of macrophages on tumor cells through the common L–R pairs (TNFSF12–TNFRSF12A and SPP1–CD44), we further calculated the correlation between the TNFRSF12A or CD44 expression and hallmark signature scores in cancer cells." (PMID 34676217, 2021). "Results obtained by RNA-seq demonstrate that tumours from all patients examined exhibited high levels of TNFSF12 and TNFRSF12, suggesting the activation of this pathway and pointing at its importance in PDAC." (PMID 34172716, 2021). "Other ligand-receptor pairs revealed by this analysis included TNF-TNFRSF1A sent by medium-SORL1 expressing GAMs, TNFSF12-TNFRSF12A (high-SORL1 GAMs to tumor cells), PDGFB-PDGFRA (medium- and high-SORL1 GAMs to several populations), and THY1-(ITGAM + ITGB2) received by high-SORL1 GAMs (Fig. EV2B)." (PMID 38499808, 2024). "TNFSF12 has been confirmed to modulate tumor progression through interacting with macrophage." (PMID 37122693, 2023). "TNFSF12 also induced apoptosis in Gefitinib resistant tumor cells." (PMID 35264191, 2022). "TNFSF12 (TWEAK) can promote cell death in tumor cell lines under certain conditions, and may also activate local macrophages to inhibit tumor progression." (PMID 28122328, 2017). "Moreover, CellChat analysis unveiled diverse and extensive interactions between disulfidptosis-mediated TME subgroups and tumor epithelial cells, highlighting the TNFSF12-TNFRSF12A ligand-receptor pair as mediators between DSTN+CD4T-C1, FLNA+CD4T-C2, and epithelial cells." (PMID 38292868, 2024). "Of particular interest, the interactions of signaling pairs TNFSF12-TNFRSF12A mediated the interaction of both DSTN+CD4T-C1 and FLNA+CD4T-C2 subgroups with tumor epithelial cells." (PMID 38292868, 2024). "We discovered the opposite roles of TNFSF12 (TWEAK) in eCAFs/myCAFs and p-EMT tumor cells in non- vs. metastasis conditions." (PMID 35742914, 2022). "Additional repressed genes were ANGPTL2, TGM2, IL-6, CSF1R, TNFSF12 as well as a key regulatory MAP kinase ERK1/2 (MAPK3), all known to stimulate chronic inflammatory signaling in the tumor microenvironment and to promote cancer metastasis." (PMID 24498382, 2014). "Moreover, CellChat analysis unveiled ligand-receptor pairs mediating communication between tumor epithelial cells and disulfidptosis-related TME subgroups, such as TNFSF12-TNFRSF12A, TNF-TNFRSF1A, OSM-(OSMR+IL6ST), OSM-(LIFR+IL6ST), HBEGF-EGFR, and EREG-EGFR." (PMID 38292868, 2024). "The TWEAK cytokine, TNFSF12, is a member of the TNF superfamily that is widely expressed in several tissues and cell types including fibroblasts, immune, mesenchymal, endothelial and tumour cells." (PMID 38965263, 2024).
tumor (continued). "Besides, MIF-EGFR/TNFRSF14, IGF1/2-IGF1R/2 R, TNFSF12-TNFRSF12A (TWEAK-Fn14) interactions also mediated the crosstalk between TPF or SLF with EPCs, consistent with their function in facilitating tumor progression." (PMID 36198671, 2022). "TNFSF12, also known as TWEAK or CD255, belongs to the tumor necrosis factor (TNF) superfamily, which is expressed in various types of cancer and has been reported to stimulate tumor growth and angiogenesis." (PMID 35602610, 2022).
cancer (74 papers, 2011 to 2025). A tumor composed of atypical neoplastic, often pleomorphic cells that invade other tissues. "PDAC cancer cells (cluster 2) expressed receptors for SPP1, MDK, and TWEAK (TNFSF12), with TWEAK showing the strongest interaction (blue frame)." (PMID 41228323, 2025). "Taken together, our results of the paracrine interactions analysis and in vitro experiment highlight the cancer-promoting role of SPP1 and TNFSF12 signaling." (PMID 34676217, 2021). "Implied by these findings, the STAT4 gene may induce STAT4+T cell infiltration through TNFSF12‐TNFRSF12A and TNF‐TNFRSF1A, further activating PANoptosis in epithelial cells and inhibiting cancer progression." (PMID 41284376, 2025). "For example, TNFSF12-TNFRSF12A and SPP1-CD44 were shown in LC, CRC, and SCC, indicating that myeloid cells might express and secrete TNFSF12 and SPP1, signaling to their receptors TNFRSF12A and CD44 on cancer cells, respectively." (PMID 34676217, 2021). "Because WA predominantly increased DNA methylation, we mainly focused on verification of hypermethylation effects obtained for selected genes related to cancer invasiveness (ADAM8, PLAU, and TNFSF12), detoxification (GSTM1) or mitochondrial functions (ME3), in relation to gene expression silencing." (PMID 28467815, 2017).
infection (19 papers, 2013 to 2025). The state of being infected such as from the introduction of a foreign agent such as serum, vaccine, antigenic substance or organism. "The expression of TNFSF12 by macrophages in response to infection helps to modulate the innate inflammatory response." (PMID 40431739, 2025). "Increased expression of TNFSF12 was observed following infection with both bovine herpesvirus 1 and bovine viral diarrhoea virus." (PMID 27479136, 2016). "We tested both TNFSF12 and ERAP1 for a role in regulating IAV infection by reducing expression with small interfering RNA (siRNA) and assessing infection using an IAV mNeon reporter strain." (PMID 36465279, 2022).
kidney disease (19 papers, 2009 to 2024). "Blocking or deleting TNFSF12/TWEAK or its receptor induces a drop in inflammation and an improvement of renal function in several experimental models of renal disease." (PMID 35806457, 2022).
metabolic disorders (3 papers, 2021 to 2025). "TNFSF12 could promote mitochondrial fusion in GO, keep energy metabolism in balance and protect against metabolic disorders." (PMID 34572446, 2021).
myopathy (3 papers, 2018 to 2025). A disease of the muscle in which the muscle fibers do not function properly. "Several tumor necrosis factor (TNF) superfamily genes (TNFSF8, LTB, TNFSF12, TNFSF13B, TNFSF14, TNFSF13, EDA) were upregulated, with LTB and EDA reaching higher levels than in other inflammatory myopathies." (PMID 41441888, 2025).
CNS tumours (1 paper, 2020). "In silico analysis showed that TNFSF12 gene is highly upregulated in several samples of CNS tumours, including GB (grade IV)." (PMID 32878880, 2020).
TNFSF12 also shares sentences with these, for which no sentence is quoted: lupus (23 papers); multiple sclerosis (12); cardiovascular diseases (11); asthma (9); nephritis (8); liver fibrosis (7); acute kidney injury (6); Cachexia (6); chronic kidney disease (6); myocardial infarction (6); neurological diseases (6); prostate carcinoma (6); renal fibrosis (6); experimental autoimmune encephalomyelitis (5); inflammatory skin disease (5); melanoma (5); type 2 diabetes (5); atopic dermatitis (4); Autoimmunity (4); sarcopenia (4); Sepsis (4); systemic sclerosis (4); Alzheimer disease (3); brain diseases (3); colitis (3); colorectal cancer (3); cutaneous lupus erythematosus (3); inflammatory bowel disease (3); liver disease (3); lymph node metastasis (3).
A further 129 diseases each share a sentence with TNFSF12 in 3 papers or fewer.